IFNG (interferon gamma)
Diseases named in the same sentence as IFNG in open-access papers (continued):
Sharing a sentence is not in itself a finding about the gene and the disease.
COVID-19 (continued). "This study aims to perform a systematic evaluation and meta-analysis of the effects of IFNL4, ACE1, PKR, IFNG, and MBL2 in the course of severe COVID-19." (PMID 35623072, 2022). "The lung tissues of patients with COVID-19 were enriched with CCR6 and IL-17A co-expressing cells, and high concentrations of IL-6, IL-17A, GM-CSF, and IFNγ were found in the liquid fraction of BALF." (PMID 35632823, 2022). "Using flow cytometry, it was shown that T cell subsets, which play a major role in the orchestration of the whole adaptive immune response, such as IFNg+ and triple+CD4+, were significantly lower in COVID-19-naive older participants." (PMID 36140549, 2022). "This study will systematically evaluate the impact of IFNL4, ACE1, PKR, IFNG, and MBL2 in the course of severe COVID-19 using electronic databases and paper-based literature with an eye to the current genetic profile of the severe COVID-19 population." (PMID 35623072, 2022). "The overexpression of proinflammatory cytokines, such as IL-1, IL-6, IL-12, Interferon gamma (IFN-γ), and TNF-α, preferentially targets lung tissue but it is also responsible of progressive multi organ failure, typical of severe cases of COVID-19." (PMID 34067872, 2021). "Of note, neutralizers of IL17, IL6, IL1, IFNA, IFNG, and TNF were predicted as antagonists of COVID-19 biology." (PMID 33782412, 2021). "In particular, for the severe and durable COVID-19 patient (HL27), while all functions were represented in TRM in a remarkably higher proportion than in blood, IFNγ in response to S peptides dominated." (PMID 34021148, 2021). "It is also noteworthy that IFNγ- and TNFα-producing MAIT cells were more numerous in COVID-19 patients who died compared with those who recovered." (PMID 34638950, 2021). "We noted a substantial increase in the production of pro-inflammatory markers like IFNγ (p = 0.0836), MCP-1 (p < 0.05), and Eotaxin (p < 0.05) in the COVID-19 positive patient sera from those with a smoking history compared to the non-smoking controls." (PMID 34122129, 2021). "Correspondingly, there are increased serum levels of TNF, IFNG, and IL6 in confirmed COVID-19 patients." (PMID 33737867, 2021). "Two recent papers demonstrated a correlation between the frequencies of IFNγ-producing SARS-CoV-2-reactive T cells and COVID-19 severity." (PMID 34228322, 2021). "Notable UPRs of COVID-19 blood included IFNA, IFNG, multiple growth factors and ligands, HIF1A, CSF1 and CSF2." (PMID 33782412, 2021). "In COVID-19, the expression of the inhibitory marker KLRC1 (also known as NKG2A) leads to decreased NK cells cytotoxic activity by affecting the IFNγ and TNFα pathways." (PMID 34603282, 2021). "Furthermore, it has also been demonstrated that COVID-19 patients are markedly characterized by elevated serum levels of pro-inflammatory cytokines; for instance, interleukin (IL)-1, IL-6, IL-12, interferon-gamma (IFN-γ) and tumor necrosis factor-alpha (TNF-α)." (PMID 38624830, 2021). "However, levels of IFN-γ which is not known to be strongly associated with KD is markedly increased in PIMS-TS as well as COVID-19, signifying that IFNγ may be important in the pathogenesis of PIMS-TS and COVID-19, thus implying the role of T- cells, NK- cells and macrophages." (PMID 33813138, 2021). "Compared with that in the non-COVID-19 group, the levels of Interleukin-2 (IL-2), Interleukin-6 (IL-6), Interferon-gamma (IFN-γ) and tumor necrosis factor-alpha (TNF-α) were significantly increased in the COVID-19 group (P < 0.05)." (PMID 35071136, 2021). "Using flow cytometry, we observed that specific IFNγ+ and triple+CD4+ T cells, the most important subsets in the orchestration of the whole adaptive immune response, were lower in COVID-19-naive older participants than in COVID-19-naive young adults." (PMID 34868051, 2021).
COVID-19 (continued). "Therefore, LAG3+IFNγ+CD8+ T cells may be the predominant phenotype showing exhaustion and may need to be further investigated to elucidate the pathogenic clinical severity of COVID-19." (PMID 34305939, 2021). "We detected IFNγ-expressing SARS-CoV-2-reactive CD4+ T cells in only 5% of RTx patients and in 20% of healthy individuals, but in 59% of COVID-19 patients." (PMID 34228322, 2021). "As expected, the magnitude of IFNγ, IL-2 and TNF producing effector cells was significantly elevated in COVID-19 patients." (PMID 34228322, 2021). "This complements the known anti-viral properties of IFNγ and the enrichment of these IFNγ-secreting CD4+ TEM cells during COVID-19 convalescence strongly suggests their role in mediating effective and long-lasting viral clearance." (PMID 34113347, 2021). "IFN genes IFNG and IFNE, and IFN receptors IFNAR2 and IFNGR2, were upregulated in COVID-19 vs non-COVID19, suggesting a crucial role for IFN-signaling in mounting an anti-SARS-Cov-2 response." (PMID 33473155, 2021). "Highly activated inflammatory immune responses, including Interferon-gamma (IFN-γ), interleukin-6 (IL-6), and NF-κB responses, had been reported in COVID-19 patients." (PMID 34697287, 2021). "Conversely, the frequencies of CD4+ effector cells differed: the amount of specific AIM+IFNγ+ and AIM+IFNγ+IL-2+TNFα+ (triple+) CD4+ T cells were lower in COVID-19-naive older participants than in COVID-19-naive young adults." (PMID 34868051, 2021). "Significantly up-regulated levels of cytokines and chemokines including IL1-β, IL1RA, IL10, IL9, IL8, IL7, basic FGF2, GCSF, GMCSF, IFNγ, IP10, MCP1, MIP1α, MIP1β, PDGFB, TNFα, and VEGFA in blood, have been confirmed in COVID-19 patients." (PMID 33041797, 2020). "Recent clinical investigation reveals that COVID-19 mild patients had high level of IL1B, IFNγ, CXCL10/IP-10 and CCL2/MCP-1, while patients requiring ICU admission had higher level of GCSF, CXCL10/IP-10, CCL2/MCP-1 and CCL3/MIP-1A." (PMID 32228226, 2020). "It’s important to point here that a typical immune-response to viral infection is interferon-gamma (IFN-γ), which represents an important cross-talk between COVID-19 and MSCs." (PMID 33102489, 2020). "In COVID-19 patients, the majority of the CD73-CD8+ T cells were capable of secreting granzyme B, perforin, tumor necrosis factor (TNF-α) or interferon-gamma (IFN-γ)." (PMID 32707842, 2020). "The early study suggested that, with ensuing local inflammation of lung affected areas, secretion of the pro-inflammatory cytokines and chemokines was increasing, such as IL-6, IFNγ, M-CSF, and MCP1, and these would release into the blood of COVID-19 patients." (PMID 32903864, 2020). "Low IFNγ response to the SARS-CoV2 and high levels of immunosuppressive IL-10 in both COVID-19 and dengue during early illness are indicators of an altered antiviral response potentially contributing to disease severity." (PMID 33199778, 2020). "COVID-19 patients were noted to have high amounts of IL1B, IFNγ, IP10 and MCP1 which were leading to activation of T-helper-1 (Th1) responses and the resulting cytokine storm was associated with disease severity." (PMID 33042116, 2020). "Overall, the CD4+ T cell response in acute COVID-19 cases largely consisted of TFH cells and IFNγ-producing cells, consistent with proper antiviral polarization." (PMID 33010815, 2020). "Higher percentages of CD4+ T cells producing IFNγ, TNFα, IL-2, and IL-17A and CD8+ T cells producing IL-2 and IL-17A have been detected by flow cytometry in PBMCs from COVID-19 patients vs. healthy controls after in vitro stimulation." (PMID 33634100, 2020). "NK cells and CTLs from COVID-19 patients exhibit increased expression of inhibitory receptor NKG2A and decreased expression of CD170a and effector molecules such as interferon gamma (IFNγ), TNF-α, and granzyme B, suggesting a state of exhaustion." (PMID 33137165, 2020).
COVID-19 (continued). "Low IFNγ response to the SARS-CoV2 and high levels of immunosuppressive cytokines such as IL-10 in both COVID-19 and dengue during early illness is likely to result in an altered antiviral response." (PMID 33199778, 2020). "The inflammatory and immune responses triggered by COVID-19 involve various cytokines and immune cells, including but not limited to interleukin (IL)-6, tumor necrosis factor-alpha (TNF-α), IL-1β, IL-8, IL-10, IL-12, IL-17, IL-23, and interferon-gamma (IFN-γ)." (PMID 39886482, 2025). "Besides, our study also describes a lesser expression of IFNγ in PHD2D4E;C127S T cells under normoxia, indicating a higher chance of infection with COVID-19 and a similar type of response by these mutant cells against dengue." (PMID 40570045, 2025). "Protective titers of antibodies and interferon-gamma against severe COVID-19 outcomes have not been established." (PMID 39857737, 2025). "In COVID-19, the immune response of lymphocytes is mediated mainly by CD4+ T cells, which differentiate into type 1 T helper (Th1) cells and are responsible for producing antiviral cytokines such as interferon-gamma (IFN-γ)." (PMID 39859379, 2025). "Referred to as hybrid immunity, slightly more than half of the individuals with previous COVID-19 still exhibited no detectable IFNγ-producing cells (0 SFU) in response to the Spike protein, classifying them as non-responders." (PMID 40699035, 2025). "In contrast, the number of IFNG+ cells was not significantly increased in patients with COVID-19, validating findings from scRNA-seq." (PMID 39567718, 2024). "The CD8+IFNγ+/million CD3+ values were higher in MISC_A compared to convalescent COVID-19 (p-value: 0.03) but were not significantly higher compared to MISC_C (p-value: 0.08) and compared to healthy controls (p-value: 0.08)." (PMID 39594853, 2024). "The low IFNγ response to SARS-CoV-2 and high levels of immunosuppressive IL-10 in COVID-19 and dengue during the early phase of illness indicate a poor antiviral reaction that could contribute to disease severity." (PMID 39519178, 2024). "Resiquimod induced significant IFNα and IFNγ at day 7 and day 28 compared to PBS in COVID-19+ PBMC." (PMID 38543837, 2024). "However, while most of the immune parameters that are deregulated during acute COVID-19 become normal after the resolution of the infection, people with PCC show persistently exhausted T cells with reduced memory subsets and increased IFNγ production." (PMID 39257580, 2024). "Moreover, attention should be paid to the boosted levels of IFNG and TNF in COVID-19, as synergism of TNF-α and IFNG triggers inflammatory cell death, tissue damage, and mortality in SARS-CoV-2 infection." (PMID 39066192, 2024). "Using a pseudobulk approach, IFNG (IFN-γ gene) in T cells was not different between patients with COVID-19 and patients with LRTD." (PMID 39567718, 2024). "In severe cases of COVID-19, a so-called cytokine storm is observed, during which the body produces excessive amounts of pro-inflammatory cytokines such as IL-6, IL-1β, TNF-α, and interferon-gamma (IFN-γ)." (PMID 39597882, 2024). "In blood, there was upregulation of inflammatory (AREG) and vascular damage (NDRG1) genes in COVID-19 in monocytes but no upregulation of IFNG or IFN-γ response genes." (PMID 39567718, 2024). "However, an IFNγ-induced signature is probably present in COVID-19, since CXCL10 (in common with CXCL9), an important IFNγ-induced chemokine, is highly detectable, as previously observed in several IFNγ-mediated syndromes." (PMID 39882243, 2024). "Those CD8+ T-cells that were present were found to be highly activated in a subset of COVID-19 patients as measured by KI67 and HLA-DR+CD38 expression and appear to retain their cytotoxic capacity as measured by IFNγ, granzyme B, perforin, and CD107a production or expression." (PMID 40012912, 2024).
COVID-19 (continued). "Moreover, inefficient functionality of the overall CD8+ T-cell response, characterized by the low percentage of interferon-gamma (IFNγ+) CD8+ T cells, CD107a+ CD8+ T cells, IL-2+ CD8+ T cells, and granzyme B+ CD8+ T cells, was also detected in COVID-19 cases." (PMID 36839573, 2023). "However, TNFα/IFNγ-induced death in mice occurs within hours, whereas death from acute respiratory distress syndrome (ARDS) in COVID-19 patients happens over a much longer time." (PMID 37459541, 2023). "This was further confirmed by increased levels of circulating type I (IFNα), type II (IFNγ) and type III IFN seen in the SARS+ compared to SARS- group, with a significantly higher IFNγ in those with moderate/severe COVID-19 compared to mild COVID-19." (PMID 37261339, 2023). "Mimicking systemic inflammation as it occurs during COVID-19 by pre-stimulation of EECM-BMECs with TNFα/IFNγ still failed to allow for productive infection of EECM-BMECs with SARS-CoV-2." (PMID 37875964, 2023). "Importantly, this study revealed a striking low IL-9 level and high IFNγ/IL-9 ratio in the plasma of patients who later died compared to mild and severe cases who recovered, suggesting that this could be an important biomarker for predicting the severity of COVID-19 and post-COVID-19 syndrome." (PMID 37569646, 2023). "We therefore identified responders (Ziegler, n = 18; Yoshida, n = 10) and non-responders (Ziegler, n = 16; Yoshida, n = 4) among patients with mild to severe COVID-19, defined as those with or without IFNG mRNA+ T cells, respectively." (PMID 37225706, 2023). "In the severe COVID-19 cohort, HIF signaling could likely be triggered by IL-6, IFNγ and growth factors (VEGF and/or EGF) as ligands of receptor tyrosine kinases." (PMID 37301958, 2023). "This exercise revealed that, whereas the DS IFN score tracks preferentially with IFNG and IFNL1 in DS, this same ISG signature correlates significantly with eight different IFNs in COVID-19, five of which are type I IFNs (i.e., IFNA2, IFNA7/17/21, IFNA1, IFNA4/16, and IFNA10)." (PMID 37379383, 2023). "Among the cytokines analyzed in response to S-peptide, some of them such as TNFα, IL-6, IL-2, IFNγ, or CXCL10 were differentially produced between naïve subjects and subjects recovered from COVID-19 early after the second vaccination dose (sample 2), with higher levels in the former group." (PMID 37153580, 2023). "Also, other studies have described increasing IFNγ-producing Th1 and a higher level of CD4+ T cell activation in COVID-19 patients, leading to worse clinical outcomes." (PMID 36493512, 2023). "The screen implicates SARS-CoV-2 M protein as a frequent target of IFNγ secreting CD8+ T cells, and identifies M198–206 as an immunoprevalent epitope in our cohort of HLA-A*24:02 positive convalescent COVID-19 patients recovering from mild, moderate and severe disease." (PMID 36526616, 2022). "This dysregulated response likely causes substantial tissue damage through cell death, both through type I IFN, which can kill via a variety of pathways and via IFNγ, which in synergy with TNF-α appears to play a detrimental role by inducing cell death during COVID-19." (PMID 35244141, 2022). "Nevertheless, we found markedly lower levels of IFNG-induced chemokine CXCL10 in KD and CXCL9 and IL15 in both KD and severe COVID-19, suggesting blunted type II interferon signaling in both KD and severe COVID-19 conditions." (PMID 36159873, 2022). "TH1-like cells from patients with mild COVID-19 exhibited a TH1 polarization state, characterized by upregulation of effector marker genes (PDCD1, CCL5, CXCR2, CCR2, GZMA/B, NKG7, PRF1, IFNG, and CCL4) and genes involved in effector function such as CXCR4, CXCL2, ANXA1, SOCS2 and LTB." (PMID 36119105, 2022). "The post hoc analysis showed a significant increase in IFNγ concentration twenty-one days after the booster, both in the group of convalescents (p = 0.001) and participants who did not previously have COVID-19 (p < 0.001)." (PMID 36146624, 2022).
COVID-19 (continued). "However, some individuals with a previous COVID-19 history demonstrated a faster immune response at 7 DAV, suggesting an influence of IFNG genetic background in vaccine immunogenicity." (PMID 36146723, 2022). "Regarding the cytokine profile of S-specific T-cells, post-COVID-19 patients with pneumonia and vaccinated subjects produced similar levels of TH1 cytokines, in particular IFNγ, IL-2, TNFα, and MIP-1β, which were significantly higher than in post-COVID-19 patients with mild symptoms." (PMID 35744768, 2022). "Additionally, resveratrol inhibits the effect of proinflammatory cytokines such as IFN-γ (interferon gamma), TNF-α and IL-1β, which play a major role in the onset of cytokine storm in COVID-19." (PMID 36421257, 2022). "Six hub genes (FCGR3A, CD69, IFNG, CCR7, CCL5, and CCL4) were involved in regulating immune cells in COVID-19 and HF, which may contribute to the pathogenesis of HF." (PMID 36420258, 2022). "Yet, key anti-viral responses such as IFNG primarily produced by cytotoxic T cells were spared, highlighting the selective effects of combined anti-IFNAR2/Remdesivir therapy on chronic COVID-19 pathology." (PMID 35483404, 2022). "Since MLKL is inducible by IFNγ in inflammatory hepatitis to promote inflammation in a RIPK3-independent fashion, MLKL may be induced by the inflammatory response in the COVID-19 lungs." (PMID 34663909, 2021). "Interestingly, comparing the frequency of double-positive (IFNγ+ TNF+) CD4+ and CD8+ T cells within individuals, these were higher in both COVID-19 patients and close contacts than in healthy controls." (PMID 33741972, 2021). "Decreased baseline serum IFNγ levels (p < 0.01) were reported in COVID-19 patients developing fibrosis (n = 46) compared to those not developing fibrosis (n = 30)." (PMID 34960806, 2021). "In young and older subjects, with or without prior COVID-19, anti-S1 IgG, neutralizing antibodies, and IFNγ-secreting T-cell levels increased from D0 to D90." (PMID 34868051, 2021). "Instead, MP_B induced significant amounts of IFNγ in the two OTD groups but not in the severe COVID-19 group." (PMID 34858405, 2021). "In a study that investigated the expression levels of several cytokine genes in leukocytes of ICU and non-ICU COVID-19 patients, it was shown that IFNg had higher expression levels in non-ICU than in ICU patients." (PMID 34836309, 2021). "The correlation analysis of specific serum biomarkers with 25OHD indicated that the vitamin D action in COVID-19 might involve regulation of INOS1, IL1B, IFNg, cathelicidin-LL37, and ICAM1." (PMID 34836309, 2021). "Our results indicated that vitamin D treatment shortened the hospitalization period, decreased the mortality rate, and that the effect of vitamin D in COVID-19 might involve regulation of INOS1, IL1B, IFNg, cathelicidin-LL37, and ICAM1." (PMID 34836309, 2021). "In all tested COVID-19 patients as well as in HD similar amounts of IFNγ spots were detected following unspecific stimulation, indicating that T cell functionality is not impaired due to COVID-19." (PMID 34194438, 2021). "Generally, COVID-19 vaccine candidates have induced low T cell responses in mice, with IFNγ+ responses of 0 to 2% and 0 to 1% among CD8+ and CD4+ T cells, respectively, or 1000 to 2000 SFCs/1 × 106 splenocytes by IFNγ ELISpot." (PMID 33547083, 2021). "Furthermore, in severe COVID-19 cases a decrease in CD8 + T cells was reported, while inflammatory cytokines (IL-6, IL-10, IL-2 and interferon-gamma (IFNγ)) increased in peripheral blood." (PMID 33921724, 2021). "Usually, patients who have COVID-19 have a decreased number of helper T cells, cytotoxic T cells, regulatory T cells, and natural killer (NK) cells, but increased leptin, TNF-α, interleukin-1 (IL-1), interleukin-2 (IL-2), and interferon-gamma (IFN-γ)." (PMID 34064950, 2021).